RNU6-788P (RNA, U6 small nuclear 788, pseudogene)
Gene: Small nuclear RNA gene on chromosome 3 (23,641,489 to 23,641,592, reverse strand). Ensembl gene ENSG00000212269.
Homologues: Orthologues: chimpanzee U6 (99% identical), macaque U6 (88% identical). Paralogues in human: RNU6-1117P (84% identical), RNU6-28P (84% identical), RNU6-497P (84% identical), RNU6-529P (84% identical), RNU6-810P (84% identical), RNU6-1083P (83% identical), RNU6-1094P (83% identical), RNU6-242P (83% identical), RNU6-38P (83% identical), RNU6-1124P (82% identical), RNU6-11P (82% identical), RNU6-1310P (82% identical), and 1285 more.